HMGB1 (high mobility group box 1)
Diseases named in the same sentence as HMGB1 in open-access papers (continued):
Sharing a sentence is not in itself a finding about the gene and the disease.
cancer (continued). "Moreover, the models also predict that mutations of RAS, ARF and P21 in the context of HMGB1 signaling can influence the cancer cell's fate - apoptosis or survival - through the crosstalk of different pathways." (PMID 21106117, 2010). "Additionally, lenvatinib directly induced cancer cell death due to its inhibitory effects on tyrosine kinases such as FGFR, which is associated with the release of damage-associated molecular patterns, including HMGB1, from dying cancer cells, known as immunogenic cell death (ICD)." (PMID 39985645, 2025). "Therefore, higher levels of circulatory HMGB1 prior to anti-PD-1/PD-L1 antibody therapy may be associated with acceleration of cancer immunity, thereby improving the efficacy of anti-PD-1/PD-L1 antibody monotherapy." (PMID 39853458, 2025). "Oncolytic virus treatment has been reported to induce ICD in cancer cells because cancer cells infected with oncolytic virus release both pathogen-associated molecules and damage-associated molecules, such as ATP, calreticulin, and high mobility group box 1 (HMGB-1)." (PMID 38745748, 2024). "In contrast to the immediate activation of the complement system, the secretion of HMGB1 is often delayed, hours after the initial stimulation, and its level often remains elevated days after in contexts of chronic inflammation associated with auto-immunity, infection and cancer." (PMID 35572583, 2022). "Moreover, these peptides caused necrosis of cancer cells and triggered the damaged cancer cells to release potent danger-associated molecular patterns (DAMPs), such as reactive oxygen species (ROS), cytochrome c, ATP, and HMGB1." (PMID 35625834, 2022). "HMGB1 concentration in blood serum might rather be associated with this function of the protein and it has been described to be associated with prognosis in several cancer entities and might serve as a biomarker in oncolytic virotherapy." (PMID 34671818, 2022). "However, little is known regarding the effects of HMGB1 gene variants on cancer." (PMID 33628090, 2021). "After reviewing lots of literatures on HMGB1 polymorphisms, a great deal of literature and information indicate that the HMGB1 rs1045411 polymorphism might be most likely associated with increased cancer risk, though the results are controversial." (PMID 33628090, 2021). "However, the molecular mechanisms underlying the functional role of HMGB1 in determining the capability of human cancer cells to evade immune attack remain unclear." (PMID 34234778, 2021). "Cancer cells dying by immunogenic cell death release damage associated signals including adenosine triphosphate (ATP), calreticulin and high mobility group box 1 (HMGB1) that promote maturation of immature dendritic cells (DCs) adjacent to the dying cancer cells." (PMID 32937841, 2020). "Finally, the subcellular localization of HMGB1 has also been linked to cancer prognosis." (PMID 31779212, 2019). "Additionally, overexpression of HMGB1 is associated with several cancer characteristics." (PMID 29651425, 2018). "Thus, understanding the molecular bases might be important for exploring the exact role of HMGB1 in cancer, as well as developing new diagnostic biomarkers and identifying new therapeutic targets." (PMID 30049847, 2018). "Although flourishing numbers of researches have demonstrated that the existence of HMGB1 polymorphism made it possible for affecting the susceptibility, prognosis as well as treatment response of malignancies, the correlation between HMGB1 polymorphism and risks of cancer remains controversial." (PMID 30049847, 2018). "For instance, differences in the level of HMGB1 expression have been demonstrated between precancerous and malignant lesions yet little is known regarding the joint effects of HMGB1 gene variants and behavioural exposure to cancer-causing substances on predisposition to OSCC." (PMID 28423715, 2017).
cancer (continued). "Moreover, previous studies have reported the effect of HMGB1 gene polymorphisms on human cancer susceptibility, and the polymorphisms may efficiently predict the risk of cancers." (PMID 28423715, 2017). "The secreted HMGB1 from immune cells might cause elevation of HMGB1 from the early stage cancers." (PMID 22496788, 2012). "Some studies on the HMGB1/RAGE interactions revealed that this complex played a pivotal role in neurite outgrowth through activation of two small GTPases of the Rho family, Cdc42 and Rac1, thus suggesting that HMGB1/RAGE signaling might be associated with cancer metastasis." (PMID 24710526, 2012). "This study found that FAM72B expression is generally positively correlated with the expression of most immune checkpoint genes across pan-cancers, particularly for HMGB1, which showed a positive relation to all except for READ, COADREAD, and COAD." (PMID 41153357, 2025). "During ICD, dying cancer cells release a series of damage-associated molecular patterns (DAMPs), such as calreticulin (CALR), high mobility group box 1 (HMGB1), and ATP." (PMID 41346575, 2025). "In colon cancer, HMGB1 released by cancer cells induces p38 phosphorylation via RAGE, promoting autophagy." (PMID 39963819, 2025). "This stromal-derived HMGB1 promotes the invasive and metastatic potential of cancer cells by activating the NF-κB signaling pathway." (PMID 41465435, 2025). "HMGB1 BoxA gene therapy, a treatment technology using BoxA of HMGB1 (BoxA) expression plasmid transfection, is an ideal cancer therapeutic technique that promotes normal cell DNA stability but induces a γH2AX-associated DNA break signaling cascade." (PMID 40561066, 2025). "Specifically, it has been demonstrated that HMGB1 release from dying cancer cells enhances antigen processing and presentation on dendritic cells (DCs) through the TLR4-MyD88 axis, a process that occurs during chemotherapy or radiotherapy." (PMID 41153383, 2025). "Decreased genetic stability is regarded as a major driver during cancer development and progression.HMGB1, as a DNA chaperone, plays an important role in the regulation of genetic stability." (PMID 40969278, 2025). "This process is dependent on cancer cell production of high-mobility group box 1 (HMGB1) and C5a-induced expression of HMGB1 receptors TLR4 and RAGE on PMN-MDSCs." (PMID 41300283, 2025). "First, an anti‐HMGB1 primary antibody was used for immunofluorescence staining to assess the efficacy of these treatments in inducing residual cancer cell ICD in vivo." (PMID 39664002, 2025). "To investigate the expression of HMGB1 across different tissues as well as its prognostic significance, we analysed data from the University of Alabama at Birmingham Cancer Data Analysis Portal (UALCAN)." (PMID 40975711, 2025). "This study aimed to determine if HMGB1 is released from human-derived cancer and normal cells after 131I-MIBG administration." (PMID 40583575, 2025). "On the other hand, HMGB1 inhibits DNA repair processes through its C‐terminal domain by interacting with DNA repair proteins, thereby enhancing the efficacy of anti‐cancer drugs such as cisplatin." (PMID 41354099, 2025). "Together, these findings establish HMGB1 as a central regulator of NF-κB activation in cancer, proposing a link between cellular stress and inflammation to MRPs expression-mediating therapy resistance through a convergent HMGB1–NF-κB axis." (PMID 41465435, 2025). "Once cancer cells die, they release intracellular molecules such as high-mobility group box 1 (HMGB1), adenosine triphosphate (ATP), and oxidized phospholipids, which can act as danger-associated molecular patterns (DAMPs)." (PMID 41369416, 2025). "Together, these compartmentalized functions position HMGB1 as a central node in the networks of cancer therapy resistance." (PMID 41465435, 2025). "The effect of transfected BoxA to reduce cytoplasmic and increased nuclear HMGB1 was the mechanism of lowering cancer aggressiveness of cisplatin resistance NSCLC." (PMID 40561066, 2025).
cancer (continued). "Currently, research into the HMGB1-pyroptosis axis in the context of established drug-resistant cancers remains in its infancy." (PMID 41465435, 2025). "Irradiation of malignant tumors releases an immunostimulatory protein (HMGB1), which activates dendritic cells." (PMID 39446307, 2025). "Altogether, HMGB1 is a central integrator of stress signals that governs the balance between apoptosis and pro-survival mechanisms that enable cancer cells to resist therapeutic-induced death." (PMID 41465435, 2025). "The rare abscopal effect in radiotherapy is thought to result from immune-activating damage-associated molecular patterns, such as high mobility group box-1 protein (HMGB1), released from cancer cells." (PMID 40583575, 2025). "Different mechanisms activated by HMGB1 contribute to critical cancer cell traits such as autophagy, immunogenic cell death (ICD), release of cytokines and chemokines, angiogenesis, and migration." (PMID 40804938, 2025). "HMGB1 is a nuclear protein that plays a crucial role in immune stimulation, particularly in the context of inflammation, infection, and cancer." (PMID 39789615, 2025). "HMGB1 has been shown to have contradictory effects during the initiation, progression, and treatment of cancer." (PMID 41354099, 2025). "This supports that HMGB1 functions as a potent upstream regulator of a well-established NF-κB–MRPs-therapy resistance axis, further solidifying HMGB1’s position as a central and versatile driver of therapy molecular resistance in cancer." (PMID 41465435, 2025). "As more clinical studies progress, the potential of HMGB1 as a therapeutic target for cancer warrants further validation." (PMID 41296391, 2025). "The integrated structure of the V domain and C1 domain primarily interacts with acidic ligands (such as HMGB1) and plays a specific role in cancer progression through multiple pathways." (PMID 41296391, 2025). "A primary consequence of autophagy-mediated HMGB1 release is the direct enhancement of cancer cell survival." (PMID 41465435, 2025). "Small molecules and natural compounds that directly target HMGB1 represent a promising therapeutic strategy for overcoming cancer therapy resistance." (PMID 41465435, 2025). "By integrating emerging evidence across these fields, we aim to provide readers with a comprehensive perspective on HMGB1 as a primary mediator of therapy resistance and to outline opportunities for its pharmacological targeting in cancer treatment." (PMID 41465435, 2025). "The dualistic roles of HMGB1 in cancer and inflammation highlight its complexity and potential as a therapeutic target." (PMID 41354099, 2025). "In this review, we specifically examine the roles of HMGB1 in cancer and inflammation due to its dualistic nature demonstrated in the pathological advancement of these conditions." (PMID 41354099, 2025). "New experimental evidence suggests that autophagy is essential for the release of High Mobility Group Box 1 (HMGB1) by cancer cells undergoing ferroptosis." (PMID 41153383, 2025). "Lactate-treated SCs elevated the level of HMGB1 within cancer cells, while glycyrrhizin inhibited this elevation." (PMID 40148311, 2025). "The release of HMGB1 is considered a “danger signal” that can affect the ability of cancer cells to evade host immune surveillance." (PMID 40969278, 2025). "Alongside its role in repairing therapy-induced DNA lesions, HMGB1 orchestrates a complementary cytoplasmic defense program that contributes to cancer therapy resistance through its capacity to stimulate autophagy under stress." (PMID 41465435, 2025). "Collectively, these results suggest that SCs enhance the invasion and migration of cancer cells through lactate-induced upregulation of HMGB1." (PMID 40148311, 2025). "Collectively, these findings position HMGB1 as a context-sensitive regulator of ferroptosis, which implicates cancer resistance to various therapies." (PMID 41465435, 2025).
cancer (continued). "Recently, we demonstrated that HMGB1-BoxA gene therapy (BoxA) is an ideal cancer treatment that revitalizes normal cells while promoting cancer cells’ DNA break cascade." (PMID 40561066, 2025). "The role of HMGB1 in cancer therapy resistance extends beyond its intracellular functions to encompass critical signaling activities in the extracellular space." (PMID 41465435, 2025). "Specifically, HMGB1 is implicated in inhibiting the proliferation of CRC cells, participating in autophagy, and contributing to cancer progression through the induction of pro-inflammatory factors." (PMID 41153357, 2025). "The study aim was to determine if HMGB1 can be released from damaged human-derived cancer and normal cells after administration of 131I-MIBG." (PMID 40583575, 2025). "HMGB1 functions as an autocrine/paracrine growth factor in various cancers, promoting malignant phenotypes and disease recurrence." (PMID 40699723, 2025). "Future research should be performed to prove if HMGB1 BoxA gene therapy can reverse the drug resistance of those cancers." (PMID 40561066, 2025). "Upon its release from stressed, dying, or resistant cancer cells, HMGB1 acts as a prototypical DAMP molecule, primarily functioning to alert and activate the immune system by engaging pattern-recognition receptors." (PMID 41465435, 2025). "HMGB3 depletion can sensitize cancer cells to several DNA-damaging drugs, and given the physical similarities to HMGB1, it is feasible that these two proteins have somewhat redundant functions." (PMID 41009989, 2025). "The damage-associated molecular patterns (DAMPs) released from cancer cells play a crucial role in activating immune responses, and here we monitored the related indicators, including calreticulin (CRT), high mobility group box 1 (HMGB1), and ATP." (PMID 40968370, 2025). "HMGB1 depletion along with ly294002 disrupted proliferation and invasion, whereas HMGB1 silencing enhanced cancer cell death postradiation, particularly in combination with ly294002." (PMID 40740483, 2025). "Several studies showed a significant connection between HMGB1 activity and poor prognosis across various cancers, including breast, prostate, colon, and pancreas cancer." (PMID 41009692, 2025). "HMGB1 activates cancer antigen presentation by interacting with toll-like receptors expressed on immature DCs." (PMID 39853458, 2025). "Herein, we demonstrated GCD-induced ICD in cancer cells through in vitro detection of HMGB1 release and CRT surface exposure." (PMID 40994449, 2025). "We envision a possible mechanism for cancer development and progression involving a vicious cycle of DNA damage and inflammation via HMGB1." (PMID 40244228, 2025). "Cellular immunofluorescence confirmed a significant upregulation of HMGB1 in CCA cells following co-culture with SCs that exocrine HMGB1, suggesting its potential role in exacerbating the oncogenicity of cancer cells." (PMID 40148311, 2025). "These naturally derived compounds are believed to act as immunoadjuvants by eliciting cancer stress responses and the following release of damage-associated molecular patterns (DAMPs), including CRT, ATP and HMGB1." (PMID 39987121, 2025). "Given its multifaceted role, HMGB1 has emerged as a promising therapeutic target, offering new directions for the development of novel cancer treatment strategies." (PMID 40969278, 2025). "Its specific role in cancer depends on a variety of factors, including cell type, microenvironment, and the subcellular localization of HMGB1." (PMID 41354099, 2025). "Although the function of HMGB1 has been evaluated across different types of cancer, few studies have investigated its role across different BMI classes." (PMID 40943211, 2025). "Elevated HMGB1 expression correlates with enhanced malignancy, poor prognosis, and chemoresistance across multiple cancer types." (PMID 41354099, 2025).
cancer (continued). "The molecular mechanisms resulting in reduced or lost HMGB1 expression and increased aggressiveness of HMGB1-depleted cancer cells are not fully understood." (PMID 40804938, 2025). "Collectively, these findings underscore that targeting HMGB1 through various tools can effectively dismantles the node integrating critical resistance pathways and resensitizes refractory cancer cells to various therapeutic interventions." (PMID 41465435, 2025). "This extracellular HMGB1 then activates MEK/ERK signaling in cancer cells, inducing pro-survival autophagy and conferring tamoxifen resistance." (PMID 41465435, 2025). "Targeting HMGB1 has shown promise in preclinical and clinical studies, with potential applications in anti‐cancer and anti‐inflammatory therapies." (PMID 41354099, 2025). "In the context of cancer metastasis and drug resistance, HMGB1 should be considered a target therapy for HCC treatment, as evidenced in the current study and previous reports." (PMID 40331953, 2025). "It is suggested that the harmful cycle of DNA damage and inflammation significantly influences cancer development and progression through HMGB1." (PMID 40244228, 2025). "NF-κB is a key transcription factor that links inflammation with cancer and is a downstream target of HMGB1/RAGE signaling." (PMID 40277915, 2025). "Our data suggest that HMGB1 in cancer ascites suppresses PGC1α expression while activating BDK, thereby impairing BCAA utilization in C2C12 cells." (PMID 40699723, 2025). "Herein, the authors propose a vicious cycle of DNA damage and inflammation in cancer development (initiation and promotion) and progression, including conversion, via HMGB1." (PMID 40244228, 2025). "The high expression of HMGB1 in malignant cells reflected the fact that cancer cells were continuously subjected to stress or death-driven activation of the intrinsic immune system and maintenance of a chronic inflammatory microenvironment." (PMID 40535567, 2025). "Additionally, HMGB1 could be employed as a diagnostic marker for early cancer detection." (PMID 40007542, 2025). "To establish an effective cell model to study HMGB1 binding and regulatory targets in cancer cells, we overexpressed the Flag-tagged HMGB1 using a vector-based expression system in HeLa cells, and the Flag-only plasmid as control (Ctrl)." (PMID 38580917, 2024). "The present work shed light on the activity of the CXCL12/HMGB1 heterocomplex on cancer cells, particularly those with a high metastatic potential and a functional thioredoxin system." (PMID 38803493, 2024). "HMGB1 is overexpressed in many cancers, including gastric and colon cancer, and promotes cell proliferation, invasion, and metastasis." (PMID 39125651, 2024). "Within the differentially enriched and repressed proteins, one high mobility group box 1 protein (HMGB1) was associated with the immune response and poor prognosis in cancer patients." (PMID 39100092, 2024). "In these patients, local extracorporeal radiation therapy activates and promotes the maturation of antigen-presenting cells by altering various immune-related factors in cancer cells (ATP, GM-CSF, HMGB1, etc.), promoting their influx into the lymph nodes." (PMID 38398229, 2024). "Surprisingly, the spread of cancer cells in M1 patients exhibited highly significant levels of HMGB1, HSP90, and S100A9 when compared with M0 patients." (PMID 39768997, 2024). "As a cancer-promoting factor, HMGB1 is also regulated by lncRNA small nucleolar RNA host gene 16 (SNHG16)/miR-218-5p 69 and lncRNA zinc finger E-box binding homeobox 2 antisense RNA 1 (ZEB2-AS1)/miR-204 70 axis in PC." (PMID 38725864, 2024). "In colon carcinogenesis, HMGB1 expression is increased in the mucosa, and HMGB1 blood levels are correlated with cancer progression." (PMID 39125651, 2024). "For example, HMGB1 secretion recruits inflammatory cells, leading to the development of cancer in mesothelial cells." (PMID 38504159, 2024).